CD74 (CD74 molecule)
Diseases named in the same sentence as CD74 in open-access papers (continued):
Sharing a sentence is not in itself a finding about the gene and the disease.
tumor (continued). "Tumor cells were also significantly more localized within CD74 MIF and MIF CD44 neighborhoods, reinforcing the role of these regions as hubs of immune suppression." (PMID 40364843, 2025). "The results showed that, compared to the control group, MIF knockdown in SCC7 cells resulted in a reduction in tumor size, accompanied by a significant decrease in the number of both CD74+PDGFRB+ and FAP+ cells." (PMID 39891284, 2025). "Cellular interaction and immunohistochemical analysis proposed MIF‐(CD74 + CXCR4) signaling pathway as a key mechanism by which malignant cells influence immune cells within the tumor microenvironment." (PMID 40018995, 2025). "Further investigations need to clarify, especially the functional role of CD74+ DAFs in pre-cancer diseases for a tumor-restraining or tumor-promoting role." (PMID 40523922, 2025). "In solid tumors, CD74 expression correlates with inflamed tumor microenvironments and favorable responses to immune checkpoint inhibitors, positioning CD74 both as a therapeutic target and as a biomarker." (PMID 41439980, 2025). "Comparative ligand-receptor analysis comparing CAF subsets with key T cell populations revealed that Fib_CD74+–CD4T_FOXP3+/CD8T_GNLY+ interactions were significantly enhanced in tumor samples." (PMID 40948762, 2025). "On the one hand, tumor cell C1_EGFR+ and C2_STAT1+ directly act on CD8T_GNLY+ through the MDK–(ITGA4+ITGB1) axis and the MIF–(CD74+CXCR4) axis to promote tumor proliferation." (PMID 40948762, 2025). "Correlation analysis indicated that HCC patients with higher expression of CD74 in tumour tissue tended to exhibit lower expression of LSD1 and a higher number of CD8+ T cells." (PMID 40356247, 2025). "Anti-tumor TAM subsets (CD74 and CD163-CD206 phagocytic TAMs) exhibited high expression of MHCII and CSF3R, and a 3- and 7-fold increase with ACTM-838 treatment, respectively." (PMID 41048107, 2025). "After cultured for 24 h, proteins of FAP and CD74 were significantly upregulated by the tumor-conditioned medium." (PMID 39891284, 2025). "Tumor cells followed a similar trend, increasing in CD74 MIF (β = 0.219, p = 0.005) and MIF CD44 (β = 0.190, p < 0.0001), further supporting their role as hubs of immune activation and tumor presence in advanced disease." (PMID 40364843, 2025). "The results showed a significant increase in the number of colorectal CSCs in metastatic tumours and revealed interactions between CD74‐MIF and metastatic tumour tissue." (PMID 40665579, 2025). "IHC results revealed that pre‐treatment, HCC patients with low LSD1 expression exhibited increased infiltration of effective CD8+ T cells and higher levels of tumour CD74 expression." (PMID 40356247, 2025). "Apart from tumor invasion promotion, these CAFs potentially form an immunosuppressive niche through inhibition of immune cell migratory (myeloid cells) CD74-MIF and SPP1-CD44 ligand-receptor signaling interactions." (PMID 41450739, 2025). "Intriguingly, even within the same patient, intra‐tumour heterogeneity of CD74 expression was notable as well." (PMID 40356247, 2025). "Here, the tumor cells elevate expression of immune signaling MHC II molecules (CD74, HLA-DRB1, HLA-DPA1) and immune-regulating secretory proteins (REG4, AGR2, AGR3), with AGR2 and REG4 specifically upregulated in RCRC." (PMID 41450739, 2025). "Further analysis revealed that Pygo2+ CD8+ T cells primarily engage with tumor cells and macrophages through immune checkpoint receptor-ligand pairs, such as CD74, CD55, and SPP1." (PMID 40771810, 2025). "The elevation of CD74 expression in tumours induced by LSD1 deletion formed a multifaceted immune response environment, ultimately contributing to a sustained response to PD1 antibody therapy." (PMID 40356247, 2025). "CD74, known as an invariant chain of the MHC‐II complex and a receptor for MIF, is frequently associated with high expression and poor prognosis during tumour development." (PMID 40411322, 2025).
tumor (continued). "The expression level of CD74 was found to be lower in tumor tissues than in normal tissues (p < 0.001)." (PMID 40470045, 2025). "Survival analysis, gene set variation analysis, and immune cell infiltration analysis were used to investigate the relationship between CD74 expression and tumor immune response." (PMID 40470045, 2025). "In tumor studies, CD74+ neutrophils have been observed to exhibit antigen-presenting functions that induce T-cell antigen-specific responses." (PMID 40874427, 2025). "Unlike the T cell subsets, the three B subpopulations highly expressed CD74 with the ligand APP overexpressed in the tumor cells, which suggests their potential immunosuppressive relation." (PMID 40057671, 2025). "In the context of cellular communication, this finding confirmed the critical role of CD74-related signaling pathways in tumor metastasis, aligning with the results of the PPI network analysis." (PMID 41127012, 2025). "In summary, this study offers a novel perspective on the spatial and functional identity of CD74+ B cells within the PSCC tumor immune microenvironment." (PMID 41111459, 2025). "Future strategies should prioritize CD74-directed immunotherapies to counteract immune evasion and tumor survival mechanisms." (PMID 41159021, 2025). "In the unique tumor‐associated TLS microenvironment of PSCC, CD74+ B cells are activated to support antitumor immunity." (PMID 41111459, 2025). "Enhancing immunotherapy involves combining inhibitors, targeting PD-L1 and CD74, to increase tumor apoptosis." (PMID 41159021, 2025). "Based on this premise, we developed a machine learning-based radiomics model that successfully predicted the expression of CD74 in the tumor microenvironment of NSCLC and established the relationship between enhanced CT radiomics features and tumor prognosis." (PMID 40470045, 2025). "In parallel, CD74 has emerged as a dual‐modality target influencing both tumour biology and immune regulation." (PMID 40411322, 2025). "The results revealed predominant CD74 expression in the tumour cell, infiltrating lymphocytes and endothelial cells." (PMID 40356247, 2025). "When treated with recombinant MIF (rMIF) at doses in the range of 0–150 ng/ml, MCF-12A and both tumor cell lines demonstrated increased proliferation, with the strongest effect observed in cells with the highest CD74 expression which are MDA-MB-231." (PMID 41159021, 2025). "The study found that the MIF-(CD74+CD44) complex play a significant role in tumor development by promoting immune cell migration and activation." (PMID 40110199, 2025). "The results revealed markedly increased coexpression of CD74 and CD20 within TLS regions, highlighting the central position of CD74+ B cells in the tumor immune microenvironment." (PMID 41111459, 2025). "Mechanistically, CDK4/6i enhances the accumulation and activation of M1 TAMs and promotes the M2 to M1 polarization via augmented interaction of the macrophage migration inhibitory factor (MIF)-CD44/CD74 axis between tumor cells and macrophages." (PMID 41082324, 2025). "In a gene-level analysis, this pattern was consistent with the accumulation of Cd74+ and Cxcl9+ macrophages at the tumor edges and Spp1+ macrophages clustering toward the necrotic center." (PMID 41176316, 2025). "Tumor cells potentially exploit MIF-(CD74+CD44) signaling to subvert immune surveillance, wherein MIF binding impairs immune effector functions." (PMID 40948800, 2025). "CD74 promoted the formation of the tumor microenvironment through enhancing S100A8 and S100A9 production in the pancreatic cancer." (PMID 40427533, 2025). "The different roles of CD74 in immune cells and tumor cells should also be further explored in an in-depth way." (PMID 39118044, 2024). "E0771 murine TNBC cells were orthotopically injected into C57BL/6, and CD74 expression on immune cells infiltrating the tumor was determined by FACS analysis." (PMID 39576827, 2024).
tumor (continued). "CTShigh and C1Qhigh TAMs generate immunosuppressive interactions with aDTCs via predominantly secretion of SPP1, FN1, TIMP1, or upregulation of CD74, all of which foster tumor-cell metastasis." (PMID 38460015, 2024). "Several antigen presentation genes, such as Tap1 and CD74 and some regulators involved in tumor cell immunogenicity, such as Irf1, Icam1 and CD40 were also upregulated by Mi-2β knockout in vitro." (PMID 38461299, 2024). "In other cases, CD74-positive cells with different staining intensities were observed, whereas tumor cells showing an invasive morphology were strongly positive." (PMID 39001552, 2024). "Our study shows that CD74 has an essential role as a biomarker of prognosis during tumor development, which highlights the possibility of new targeted therapies." (PMID 38861249, 2024). "In order to further explore the specific receptors involved in the MIF pathway in FABP6+ tumor cells, we conducted an analysis and found a significant enrichment of CD74 and CD44 receptors in the tumor tissue." (PMID 38277205, 2024). "Studies have shown that CD74 is abnormally expressed in many tumors and is closely related to tumor immune regulation." (PMID 39118044, 2024). "To restore an effective immune response, we observed that mice receiving a combination of CD74 blockade and an immune checkpoint inhibitor (anti‐PD‐1) exhibited slower tumour growth and improved overall survival." (PMID 39113235, 2024). "Tumors with high expression level of CD74 tend to display an immune-inflamed subtype, which shows the potential in anti-tumor immune responses." (PMID 38280003, 2024). "Endothelial cells from Kmt2c KO and Kmt2d KO tumours were distinct from the WT and shared top upregulated genes, including Cd74, Cxcl9, H2-Ab1 and H2-Eb2." (PMID 38926506, 2024). "Here, we observe that human tumor-infiltrating Tregs selectively overexpress CD74, the MHC class II invariant chain." (PMID 38702311, 2024). "In our study, high CD74 expression in tumour cells exhibited a stronger capacity for tumorigenesis when using normal mouse tumour models." (PMID 39113235, 2024). "When compared with normal group, CD56bri_CCL5 cells in tumor demonstrated an increased interaction weight with macrophage cells through the MIF-(CD74+ CD44) ligand-receptor pair." (PMID 38552055, 2024). "Similar to the RNAscope results, the CD74‐202/CD74‐201 ratio in the LN significantly exceeded that in the enrichment fraction of the tumor." (PMID 39312471, 2024). "The ESTIMATE algorithm was used to explore the associations between CD74 and the tumor microenvironment (TME) by calculating the ImmuneScore, StromalScore, and ESTIMATEScore in 33 tumor types." (PMID 38582956, 2024). "We further explored how microglia regulated by the MIF/CD74 signaling axis exerts tumor-regulating effects." (PMID 38685050, 2024). "Expression of CD74 is significantly up-regulated in different cell types in various cancers and is correlated with tumor progression." (PMID 39576827, 2024). "Further analysis revealed that a critical cluster of CD74+ tumour cells, which express both epithelial and immune marker signatures, contributed to immune evasion, ultimately leading to the progression of LSCC with COPD." (PMID 39113235, 2024). "IHC staining revealed overexpression of CD74 in tumor cells compared to normal ciliated epithelial cells." (PMID 39001552, 2024). "It was found that CD74 is expressed differentially between tumor and normal tissues, suggesting its potential as an independent predictor of outcomes in many cancer types." (PMID 38582956, 2024). "Specifically, MIF can activate downstream signaling pathways such as MAPK (Mitogen-Activated Protein Kinase) and PI3K (Phosphoinositide 3-Kinase) by binding to CD74, promoting tumor cell proliferation, survival, and metastasis." (PMID 38277205, 2024).
tumor (continued). "Tumor cells that express higher levels of CD74 would survive after the initial rounds of osimertinib treatment and would then proliferate to promote tumor relapse and resistance to this therapeutic option." (PMID 39001552, 2024). "We demonstrate that CD74 expressed on CD11C+ cells regulate tumor growth through the control of the cross-talk between the tumor-infiltrating tol-DCs and Bregs." (PMID 39576827, 2024). "The current study demonstrated that the MIF - (CD74+CXCR4) ligand-receptor pair is significantly active in tumor cells with elevated IGF2BP1 expression." (PMID 39512352, 2024). "MIF can be secreted as an immunosuppressive factor in the tumor microenvironment, and blocking CD74/MIF signaling enhances CD8+ T cell infiltration and drives macrophage pro-inflammatory conversions and anti-tumor function." (PMID 38730725, 2024). "The highest levels of expression in tumor tissue were observed for CD74 (Mean ± SEM = 10.94 ± 0.08), IFI27 (Mean ± SEM = 9.63 ± 0.12), and HLA-DRA (9.3 ± 0.1)." (PMID 39457004, 2024). "It has been found that in melanoma, CD74-MIF interaction promotes tumor survival via the PI3K/AKT pathway in response to IFN-γ." (PMID 38178143, 2024). "Here, we demonstrate that CD74 enhances tumor growth by inducing the expansion of tumor-infiltrating tol-DCs and Bregs." (PMID 39576827, 2024). "By employing the mIF methods, we found an inverse relationship between the presence of CD74+ tumour cells and CD8+ T cells, as well as a correlation with the ratio of PD‐1 positive CD8+ T cells." (PMID 39113235, 2024). "The elevated levels of granzyme B+ B cells in tumor samples resulted from tumor cell chemotaxis through the MIF- (CD74 + CXCR4) signaling pathway." (PMID 38386050, 2024). "In contrast, the CD74‐KD group showed a higher proportion of progenitor‐exhausted T cells in tumour tissues compared to the Ctrl and CD74‐Over groups (F and S19A‐I)." (PMID 39113235, 2024). "Taken together, these findings highlight the influence of tumor cells chemotaxis on GrB+ B cells through the MIF- (CD74 + CXCR4) signaling pathway." (PMID 38386050, 2024). "recently demonstrated that tumour necrosis factor (TNF)‐α‐dependent lung inflammation can facilitate the upregulation of CD74 in tumour cells, promoting the proliferation and migration of LC cell lines." (PMID 39113235, 2024). "Considering the extremely high diversity of microglia subpopulations with unique gene expression profiles and different roles, more studies are needed to decipher the role of CD74 in microglia anti-tumor responses." (PMID 38178143, 2024). "For example, by performing single‐cell RNA sequencing (scRNA‐seq) and single‐cell ATAC‐sequencing analysis on both TKI‐resistant cells and clinical specimens, Kashima and colleagues identified CD74 as a novel key factor in regulating tumor drug‐tolerant state." (PMID 39184861, 2024). "Increased expression of CD44, CXCR4 and CD74 on group 1 and 2 NK cells, on which numerous signals from fibroblasts, endothelial cells, tumor cells and macrophages converged (COLLAGEN, MIF, LAMININ), facilitated the augmented incoming signaling in NSCLC." (PMID 38956379, 2024). "Further analysis revealed a critical cluster of CD74+ tumour cells that expressed both epithelial and immune cell signatures, exhibited a stronger capacity for tumorigenesis and predicted worse overall survival." (PMID 39113235, 2024). "In the context of VM, our findings reveal a propensity for increased communication involving IIF and CD74+CXCR4 within each signaling pathway in the tumor group." (PMID 39165361, 2024). "The expression of the receptors CXCR4 and CD74 was markedly increased in tumor cells, suggesting activation of the MIF signaling pathway in tumors." (PMID 38191424, 2024). "The difference we observed raised an interesting question about the previously reported performance of CD74 protein expression on tumor cells and/or total cells." (PMID 38280003, 2024).
tumor (continued). "Subsequently, we analysed a cohort of LSCC from the TCGA and found that a high expression level of CD74+ tumour cells was correlated with a worse overall survival." (PMID 39113235, 2024). "Blocking CD74 leads to a reduced tumor load due to the elevated activity of the tumor-infiltrating immune cells." (PMID 39576827, 2024). "Regulatory changes in CD74 and HLA-DM have been shown to lead to significant remodeling of the tumor microenvironment." (PMID 39917362, 2024). "Among the interaction molecular pairs, tumour invasion‐related pairs, including CD74_MIF, SPP1_CD44, were enriched among macrophages and MYH11+ CAFs." (PMID 39294858, 2024). "Hepatocyte-specific MIF-KO and global CD74 KO mice exhibited reduced tumor burden compared to their WT counterparts." (PMID 38732068, 2024). "Among them, CD4_C3_CXCL13 T cells emerged as the most extensive communicative with HPV+ tumor cells, especially through CD74-COPA, CD74-MIF and CD2-CD58, which play a critical role in MHC-II antigen presentation and T cell activation." (PMID 39105803, 2024). "Our study revealed a potential link between tumor immunity and the expression of CD74 and revealed its important prognostic value for HCC patients receiving immunotherapy." (PMID 39118044, 2024). "The interaction between MIF and CD74 can trigger various signaling pathways related to tumor cell survival and proliferation, such as PI3K/AKT and NF-κB pathways, playing a downstream role in cell survival and proliferation." (PMID 39474111, 2024). "CD74 therefore emerges as a specific regulator of tumor-infiltrating Tregs and as a target to interfere with Treg anti-tumor activity." (PMID 38702311, 2024). "Remarkably, we identified a critical cluster of CD74+ tumour cells that exhibited both epithelial and immune signatures in LSCC with COPD." (PMID 39113235, 2024). "When the recruiter CAF_CCL21 is deficient, the loss of the CXCL12-CXCR4 axis recruitment impairs the infiltration of B_CD74 responders, disrupting B cell-mediated antigen presentation and suppressing the anti-tumor effect of CD8+ T cells." (PMID 38505619, 2024). "In this study, we found that high CD74 concentration in HPCs was associated with a decreased proportion of CLEC9A(+) DCs, which suggested a potential tumor-promoting role of CD74 in HPCs." (PMID 39118044, 2024). "Both TMSB10 and GPX1 were expressed on significantly higher numbers of disseminated hybrid cells compared to circulating tumor cells, and CD74 and GPX1 were expressed on more disseminated hybrids than tumor-resident hybrids." (PMID 38106024, 2023). "In the analysis of L/R pairs, the L/R pairs of MIF/(CD74 + CD44 or + CXCR4) and APP/CD74 were the most prominent interactions involving signal transduction from tumor cells to PCs." (PMID 37138324, 2023). "The Western blot of five patients’ tumor tissues and normal tissues also showed a clear increase in CD74 expression in the former." (PMID 37629174, 2023). "Macrophage migration inhibitory factor (MIF) is a well-characterized immunosuppressive factor that is secreted by immune cells and plays an important role in tumour immune escape by binding to its receptor CD74." (PMID 37491279, 2023). "The elevated expression of CD74 can be a marker of tumor progression as well as poor clinical prognosis." (PMID 37958963, 2023). "CD74 expression in nonhematologic malignancies has been considered to be a prognostic factor, with elevated CD74 as a marker of tumor progression or poor clinical outcome." (PMID 37147569, 2023). "Recent studies reported on the high expression of CD74 in several types of tumor tissues and revealed that CD74 activation leads to increased proliferation and epithelial-to-mesenchymal transition and decreased apoptosis." (PMID 37629174, 2023). "Interactions of tumor cells with the BM microenvironment involve preferred communication with myeloid cells through the MIF/CD44/CD74/CXCR4 and MK/LRP1/NCL axes." (PMID 37365178, 2023).